ALK (ALK receptor tyrosine kinase)
Diseases named in the same sentence as ALK in open-access papers (continued):
Sharing a sentence is not in itself a finding about the gene and the disease.
lung adenocarcinoma (continued). "For example, mutations of KRAS and NRAS predict resistance to anti-EGFR antibodies in colorectal cancers, and patients with lung adenocarcinoma that harbor EGFR mutations or ALK rearrangements have shown remarkable efficacy in relevant targeted drug therapy." (PMID 36741696, 2022). "Young (adjusted OR 3.947, 95% CI 1.873–8.314, P < 0.001) and lung adenocarcinoma (adjusted OR 2.950, 95% CI 0.998–8.719, P = 0.050) were associated with ALK/ROS1 fusions." (PMID 35081265, 2022). "We sought to characterize the genomic landscape associated with CDKN2A deletion in EGFR/ALK- lung adenocarcinoma specimens using the Foundation Medicine genomic dataset." (PMID 35739333, 2022). "Young (adjusted OR 3.947, 95% CI 1.873–8.314, P < 0.001) and lung adenocarcinoma (adjusted OR 2.950, 95% CI 0.998–8.719, P = 0.050) were independent variables associated with ALK/ROS1 gene fusions." (PMID 35081265, 2022). "This study demonstrated that PET/CT radiomics-based machine learning model has potential to be used as a non-invasive diagnostic method to help diagnose ALK mutation status for lung adenocarcinoma patients in the clinic." (PMID 33738250, 2021). "Although several studies have investigated relationships between CT imaging features and EGFR mutation and ALK status, such associations in lung adenocarcinoma are conflicting due to the small sample sizes." (PMID 33707479, 2021). "Differential ALK inhibitor responses were observed among intragenic rearrangements variants in ALK-positive lung adenocarcinoma (case 5, case 6 and case 8)." (PMID 34271921, 2021). "On the other hand, the mother, also a carrier of the GRHL2 variant, was recently diagnosed with ALK-positive lung adenocarcinoma." (PMID 33810548, 2021). "A limited number of reports have focused on the association between ALK positivity and CT features because of the low rate of ALK positivity in lung adenocarcinoma." (PMID 33707479, 2021). "In particular, the third generation anti-EGFR osimertinib is currently recommended for patients with EGFR-mutated lung adenocarcinoma, alectinib, or brigatinib for those harboring ALK rearrangements, and crizotinib for those with ROS1 rearrangement." (PMID 33435440, 2021). "In our cohort, 9 of 152 patients with stage IV lung adenocarcinoma had positive ALK gene fusion mutations, with a mutation rate of 7.24%, slightly higher than the reported level." (PMID 33997043, 2021). "Activating mutations in epidermal growth factor receptor (EGFR) and anaplastic lymphoma kinase (ALK) rearrangement are the major driving force for lung adenocarcinoma while most squamous cell carcinomas display somatic mutation of p534,6–8." (PMID 33833226, 2021). "The incidence of ALK gene fusion mutation was about 3.8% in the Asian lung adenocarcinoma population." (PMID 33997043, 2021). "The two most common druggable targets are epidermal growth factor receptor (EGFR) mutations and anaplastic lymphoma kinase (ALK) rearrangement in lung adenocarcinomas." (PMID 33707479, 2021). "Approximately 3–7% of patients with lung adenocarcinoma have the echinoderm microtubule-associated protein-like 4 (EML4)/ALK fusion gene." (PMID 33435596, 2021). "Our findings provided a new perspective for understanding the underlying mechanisms for ALK-translocated lung adenocarcinoma to survive from crizotinib treatments." (PMID 32164629, 2020). "Specific targeted agents like gefitinib, afatinib, osimertinib (for EGFR mutated tumors) and crizotinib/ceritinib (for ALK rearranged lung adenocarcinomas) have been approved by the Food and Drug Administration (FDA) for clinical use." (PMID 32149365, 2020). "The association between CT features and EGFR mutation or ALK positivity in single primary lung adenocarcinoma (SPLA) has been well established and indicates a certain correlation between imaging and gene expression in SPLA." (PMID 32690092, 2020).
lung adenocarcinoma (continued). "Here we report a rare double ALK fusion variant, EML4-ALK and CDK15-ALK in a patient with lung adenocarcinoma who responded well to crizotinib." (PMID 33157918, 2020). "This coincides with the finding that ALK mutations were more common in lung adenocarcinoma of stages III and IV in the univariate analysis." (PMID 32266148, 2020). "The promising performance of the radiomic model in our study indicates that radiomic features extracted from non-enhanced CT images are adequate for establishing a convincing predictive model for ALK mutations in lung adenocarcinomas." (PMID 32266148, 2020). "This suggests the strong efficacy of radiomics as tools to identify ALK-mutated tumours' phenotypic patterns on CT scans in lung adenocarcinoma patients." (PMID 32266148, 2020). "Epidermal growth factor receptor (EGFR) mutations and anaplastic lymphoma kinase (ALK) rearrangement are the two most common druggable targets in lung adenocarcinoma." (PMID 32690092, 2020). "More studies are warranted to establish a tight connection between these two features and ALK mutations status in lung adenocarcinomas." (PMID 32266148, 2020). "This case demonstrates the rare finding of an ALK-mutated lung adenocarcinoma with ovarian metastasis and, to our knowledge, it is the first with an occult lung adenocarcinoma primary." (PMID 32864261, 2020). "In western countries, rearrangements in the gene (ALK) encoding anaplastic lymphoma receptor tyrosine kinase have been found in only 3–7% of lung adenocarcinomas; in contrast, EGFR mutation is approximately 10–15%, more frequent than ALK rearrangement." (PMID 31455365, 2019). "In comparison to EGFR-mutated or WT lung adenocarcinomas, ALK-positive tumors had a higher expression of PD-L1 and a higher number of intra-tumoral CD8+ T cells or PD-1+ CD8+ T cells." (PMID 30326973, 2018). "Driver oncogenes, such as ROS1 rearrangement, EGFR mutation, and ALK rearrangement, should be examined in putative lung adenocarcinoma similar to that in primary lung adenocarcinoma." (PMID 30443294, 2018). "Detecting somatic mutations within epidermal growth factor receptor (EGFR) and anaplastic lymphoma kinase (ALK) driver gene status has become a diagnostic routine for lung adenocarcinoma." (PMID 29642919, 2018). "Patient 19 presented a lung adenocarcinoma with an ALK G1202R variant, a mutation associated with general resistance against ALK inhibition." (PMID 30373609, 2018). "In 2007, anaplastic lymphoma kinase (ALK) was the first gene reported to cause lung adenocarcinoma upon a chromosomal rearrangement resulting in a fusion gene." (PMID 28881815, 2017). "Tyrosine kinase inhibitors (TKIs) are widely used to treat lung adenocarcinoma patients with EGFR mutations or ALK-fusions." (PMID 29285248, 2017). "Aim of this study was to investigate the role of epidermal growth factor receptor (EGFR) and anaplastic lymphoma kinase (ALK) mutational status on the risk of venous thromboembolism (VTE) in lung adenocarcinoma." (PMID 28560038, 2017). "In public dataset GSE31210, low FSTL1 RNA level was associated with lung adenocarcinoma patients with ALK-fusion or KRAS mutation compared to those with EGFR mutation or EGFR/KRAS/ALK triple-negative tumors." (PMID 28852126, 2017). "The clinical characteristics of patients with ALK-positive lung adenocarcinoma were similar to those of EGFR-mutated patients." (PMID 29156778, 2017). "EGFR mutations and ALK gene fusion were thought to be mutually exclusive events in lung adenocarcinoma." (PMID 27352172, 2016). "And in another study, EGFR mutations and ALK rearrangements were also found in lung adenocarcinomas with clear cell component." (PMID 27013585, 2016). "The aim of this study was to present the EGFR, KRAS and ALK mutations in a representative cohort of patients with lung adenocarcinomas in Croatia and to correlate the mutational status with clinical data." (PMID 27655296, 2016).
lung adenocarcinoma (continued). "In other studies, it was also reported that a solid histology with signet-ring cells was significantly associated with ALK rearrangements lung adenocarcinomas." (PMID 27386342, 2016). "We employed combined testing for fusions and mutations and detected fusion of EML4 exon 13 with ALK exon 20, which is one of the most common fusion variants in lung adenocarcinomas (variant 1)." (PMID 27863497, 2016). "In conclusion, our study showed different PFS on pemetrexed treatment according to ALK fusion variant in lung adenocarcinoma." (PMID 27756333, 2016). "We present a case report of a 50-year-old man with MPE who is stage IV lung adenocarcinoma and an ALK mutation after other multiple treatments showed a good response to ceritinib." (PMID 28018791, 2016). "The main objective of the present study was to analyze the EGFR, KRAS and ALK mutation status in a representative cohort of patients in Croatia with lung adenocarcinomas and to correlate the mutational status with clinical data." (PMID 27655296, 2016). "At the other end of the mutational landscape of lung adenocarcinomas are ALK gene rearrangements, which occur in 1-6 % of NSCLCs worldwide." (PMID 27655296, 2016). "ALK gene alterations mainly occur in lung adenocarcinoma and are associated with gene rearrangements." (PMID 26373952, 2015). "Because mutations of EGFR, KRAS, HER2, BRAF, as well as ALK fusions have been well established to be existed in lung adenocarcinoma, these mutation and fusion genes that ‘drives’ lung adenocarcinoma were not screened in lung squamous cell carcinoma." (PMID 25198510, 2014). "With the discovery of epidermal growth factor receptor (EGFR) mutations, anaplastic lymphoma kinase (ALK) rearrangements, and effective targeted therapy, personalized medicine has become a reality for patients with lung adenocarcinoma." (PMID 25505733, 2014). "ALK+ was associated with younger age and lymph node metastasis in this Chinese lung adenocarcinoma patient cohort." (PMID 24422905, 2014). "We have screened the prevalence of known driver mutations of EGFR, KRAS, HER2, BRAF and ALK in a cohort of 107 lung adenocarcinoma sample with complete prognostic information." (PMID 25198510, 2014). "EGFR, KRAS, HER2, BRAF mutation and ALK fusion were mutated in 25.2%, 6.5%, 1.9%, 0.9% and 3.7% of lung adenocarcinomas." (PMID 25198510, 2014). "In conclusion, our work illustrated the mutation spectrum of EGFR, KRAS, HER2, BRAF and ALK in lung adenocarcinoma, as well as confirmed that hTERT 5′ promoter region mutation rarely occurred in NSCLC samples." (PMID 25198510, 2014). "In our study, ALK-rearranged lung adenocarcinomas were associated with characteristic morphology such as cribriform structure, prominent extracellular mucus, and any type of mucous cell pattern." (PMID 23922677, 2013). "In this study, we performed a detailed comprehensive analysis of the histomorphological features associated with ALK-rearranged lung adenocarcinoma based on comparisons with well-known driver oncogene mutations." (PMID 24194854, 2013). "On the other hand, echinoderm microtubule-associated protein-like 4 (EML4)-anaplastic lymphoma kinase (ALK) fusion gene in a subset of lung adenocarcinoma is related to mucinous cribriform histology." (PMID 23617234, 2013). "When compared with pan-negative tumors, only cribriform structure, prominent extracellular mucus and any type of mucous cells were significantly associated with ALK-positive lung adenocarcinomas." (PMID 23922677, 2013). "Examples include the use of epidermal growth factor receptor (EGFR) inhibitors such as gefitinib and erlotinib for lung adenocarcinomas bearing EGFR mutations, and of ALK inhibitors such as crizotinib for lung adenocarcinomas bearing EML4-ALK translocations." (PMID 21666749, 2011). "For example, HER2-positive breast cancer and ALK-positive lung adenocarcinoma may increase RN risk, BRAF-mutated melanoma has been linked to a lower incidence." (PMID 41228337, 2025).
lung adenocarcinoma (continued). "The study concluded that specific radiological and pathological characteristics, along with EGFR and ALK mutation statuses, could be used to guide the treatment and diagnosis of lung adenocarcinoma." (PMID 41378298, 2025). "We suggest that future research should investigate the biological mechanisms by which the peritumoral microenvironment influences ALK mutation status, as this could reveal new therapeutic targets and improve treatment precision for lung adenocarcinoma." (PMID 40083024, 2025). "ALK gene rearrangement is associated with tumor cell proliferation, differentiation, migration, neoangiogenesis, and apoptosis, making it an important target for treating lung adenocarcinoma." (PMID 41020204, 2025). "As a result, our model may be more effective in identifying the differences in radiomics features between lung adenocarcinoma patients of different ALK mutation status." (PMID 40083024, 2025). "EGFR and ALK mutation can be seen between 12–17 and 5–7% of the lung adenocarcinoma, respectively." (PMID 38668879, 2024). "In patients with advanced lung adenocarcinoma (LADC) harboring the echinoderm microtubule-associated protein-like 4 (EML4) -anaplastic lymphoma kinase (ALK) rearrangement, targeted therapy typically demonstrates superior efficacy as an initial treatment compared to chemotherapy." (PMID 38380327, 2024). "However, another recent study found that high baseline PD-L1 expression was associated with shorter overall survival (OS) in ALK-rearranged lung adenocarcinoma." (PMID 37371571, 2023). "Anaplastic lymphoma kinase (ALK)-mutated or epidermal growth factor receptor (EGFR)-mutated lung adenocarcinoma patients with brain metastases are primarily treated with systemic molecular therapies instead of upfront brain irradiation, especially when there are few and small lesions in the CNS." (PMID 38370347, 2023). "At present, the research progress of targeted therapy for epidermal growth factor receptor (EGFR) and anaplastic lymphoma kinase (ALK) gene mutations in lung adenocarcinoma is very rapid, which brings new hope for the treatment of advanced lung adenocarcinoma patients." (PMID 35340157, 2022). "At our institution, somatic mutation detection using immunochemistry and NGS Panel CLv3 and single tests for ROS1 and ALK mutations was performed for nearly all lung adenocarcinoma patients at the time of diagnosis, and finally, almost half of them had negative findings (42%)." (PMID 36292136, 2022). "Although novel ALK fusion variants have been occasionally reported in NSCLC, to our knowledge, the concomitance of double ALK fusion variants in the same lung adenocarcinoma (LUAD) patient was rare, by far, only 6 cases were reported, median age was 44 (range, 29–64 years)." (PMID 35144623, 2022). "There are differences in baseline reports of lung adenocarcinomas with ALK mutations." (PMID 34596344, 2021). "The detection of ALK mutation status using this approach might be useful for informing treatment strategies for lung adenocarcinoma patients." (PMID 33738250, 2021). "Second, this predictive model was constructed based on PET/CT scans from a selected population of lung adenocarcinoma patients in one single medical center, results derived from this model cannot represent broad ALK mutation status of the general lung adenocarcinoma population." (PMID 33738250, 2021). "Second, EGFR mutation and ALK gene fusion are mutually exclusive events in lung adenocarcinoma." (PMID 34559836, 2021). "The aim of the current study is to construct a machine learning model that can be used to non-invasively and automatically detect ALK mutation based on PET/CT images from tumor lesions of lung adenocarcinoma patients and clinical characteristics of these patients." (PMID 33738250, 2021).
lung adenocarcinoma (continued). "For accurate diagnosis and treatment, a special staining method was applied to the lung adenocarcinoma tissue—immunohistochemical (IHC) staining to detect PD-L1 (Programmed death-ligand 1) and ALK (Anaplastic Lymphoma receptor tyrosine Kinase) mutation for our patient." (PMID 33801895, 2021). "However, a successful pembrolizumab treatment case of lung adenocarcinoma after becoming resistant to ALK-TKI treatment due to G1202R mutation was reported." (PMID 34660278, 2021). "Here, we proposed that a novel machine learning model based on radiomic features of PET/CT images and clinical characteristics could be used to predict ALK mutation status in lung adenocarcinoma patients." (PMID 33738250, 2021). "Nevertheless, the integrated model developed in the current study may serve as a preliminary model to support future prospective studies using machine learning algorithms to identify ALK mutation status for lung adenocarcinoma patients." (PMID 33738250, 2021). "When taken together, we may reasonably consider that ALK-positive lung adenocarcinoma is associated with high invasion." (PMID 33707479, 2021). "In this study, we developed an integrated model that combined radiomic features, clinical data and conventional CT features (AUC = 0.88, accuracy = 0.79, sensitivity = 0.82, and specificity = 0.78 in the independent test cohort) for differentiating ALK mutations in lung adenocarcinoma patients." (PMID 32266148, 2020). "Therefore, our study can reasonably conclude that MPLA tumours with EGFR mutations and ALK positivity have imaging patterns similar to single lung adenocarcinomas." (PMID 32690092, 2020). "In summary, we studied on 72 patients in stage IV lung adenocarcinoma in Hubei province and investigated the predictive value of serum tumor markers in the prediction of ALK mutations, which we cannot predict through the level of tumor markers (SCCAg, CYRF21‐1, and NSE)." (PMID 31489711, 2020). "Current smoking was strongly correlated with non-ALK-mutated lung adenocarcinoma." (PMID 32266148, 2020). "Anaplastic lymphoma kinase (ALK) translocation is an actionable mutation in lung adenocarcinoma." (PMID 30658414, 2019). "This platform is primarily demonstrated to be an accurate, noninvasive and real-time detection of ALK mutations in treatment-naive patients with stage III or IV lung adenocarcinoma, optimizing the selection of ALK-inhibitor eligible patients and the dynamic monitoring of therapy reaction." (PMID 30658713, 2019). "Alterations in EGFR, as well as in other genes such as KRAS mutations or ALK translocations, are frequent in lung adenocarcinoma; all these changes have been involved in the activation of signaling pathways critical in lung tumorigenesis, such as MAPK and PI3K/AKT pathways." (PMID 29731995, 2018). "Thus, targeted treatment is now approved for patients with EGFR-mutated and ALK-rearranged advanced lung adenocarcinomas." (PMID 30060526, 2018). "The search of mutation of EGFR and ALK and administration of appropriate targeted therapy could improve survival of patients with advanced lung adenocarcinoma." (PMID 28327204, 2017). "For the small subset of patients diagnosed with advanced lung adenocarcinoma carrying epidermal growth factor receptor (EGFR) mutations or anaplastic lymphoma kinase (ALK) rearrangements, several options including the tyrosine kinase inhibitors, erlotinib and gefitinib, are now available." (PMID 29262603, 2017). "However, we found that ALK rearrangement was associated with worse disease-free survival, tumor-specific survival, and overall survival in surgically-resected lung adenocarcinoma patients." (PMID 29156778, 2017). "It is still unknown how the EGFR and ALK mutational profile affects the risk of DVT/VTE in lung adenocarcinoma." (PMID 28560038, 2017).